HEPACAM (hepatic and glial cell adhesion molecule)
Description:
Involved in regulating cell motility and cell-matrix interactions. May inhibit cell growth through suppression of cell proliferation. In glia, associates and targets CLCN2 at astrocytic processes and myelinated fiber tracts where it may regulate transcellular chloride flux involved in neuron excitability.
Synonyms: glialCAM; FLJ25530; MLC2A; MLC2B
Tractability: Antibody: UniProt places it where antibodies can reach, with high confidence; UniProt predicts a signal peptide or a membrane-spanning region; its Gene Ontology location is reachable by antibodies, with medium confidence. PROTAC: its protein half-life has been measured.
Gene: Protein-coding gene on chromosome 11 (124,919,205 to 124,936,431, reverse strand). Ensembl gene ENSG00000165478.
Subcellular location: Cytoplasm; Cell membrane
Subcellular location (Human Protein Atlas): Vesicles
Gene Ontology:
Biological process: protein localization to cell-cell junction; immune response
Cellular component: astrocyte end-foot; cell-cell junction; cytoplasm; plasma membrane
Genetic constraint (gnomAD): Loss-of-function variants: 18 observed, 33.35 expected, observed/expected ratio (o/e) 0.54, 90% interval 0.37 to 0.8. The upper end of that interval is the gene's LOEUF score, 0.8, which puts it in group 3 of 6, group 1 being the genes least tolerant of losing a copy. Missense variants: 465 observed, 518.37 expected, observed/expected ratio (o/e) 0.9, 90% interval 0.83 to 0.97. Synonymous variants: 216 observed, 215.25 expected, observed/expected ratio (o/e) 1, 90% interval 0.9 to 1.12.
Gene-disease validity (ClinGen):
ClinGen rates the evidence that HEPACAM causes each of these diseases.
megalencephalic leukoencephalopathy with subcortical cysts 2A (autosomal recessive): Definitive.
megalencephalic leukoencephalopathy with subcortical cysts 2B, remitting, with or without intellectual disability (autosomal dominant): Definitive.
Homologues: Orthologues: chimpanzee HEPACAM (99% identical), rabbit HEPACAM (97% identical), rat Hepacam (95% identical), mouse Hepacam (95% identical), pig HEPACAM (94% identical), dog HEPACAM (94% identical), guinea pig HEPACAM (93% identical), macaque HEPACAM (90% identical), tropical clawed frog hepacam (65% identical), zebrafish HEPACAM (54% identical), zebrafish hepacama (51% identical). Paralogues in human: HEPACAM2 (22% identical), CEACAM1 (18% identical), CEACAM5 (17% identical), PSG6 (16% identical), CEACAM16 (16% identical), PSG1 (16% identical), PSG4 (16% identical), PSG7 (16% identical), CEACAM18 (16% identical), PSG3 (16% identical), PSG8 (16% identical), CEACAM8 (15% identical), and 12 more.
Diseases named in the same sentence as HEPACAM in open-access papers:
HEPACAM is named in the same sentence as 42 diseases in open-access papers, as found by Europe PMC text mining. Sharing a sentence is not in itself a finding about the gene and the disease. The quoted sentences say what the papers report.
megalencephalic leukoencephalopathy (16 papers, 2014 to 2025). "Mutations in HEPACAM give rise to the neurodegenerative disease megalencephalic leukoencephalopathy with subcortical cysts (MLC) since mutated hepaCAM prevents shuttling of MLC1 protein to astrocytic junctions in the plasma membrane." (PMID 27819278, 2016).
multiple sclerosis (12 papers, 2022 to 2026). A progressive autoimmune disorder affecting the central nervous system resulting in demyelination. "Antibodies to ENBA1 cross-react with host Hepatic and Glial Cell Adhesion Molecule (GlialCAM) proteins, which may be a driver of the autoimmunity in multiple sclerosis." (PMID 41299435, 2025).
megalencephalic leukoencephalopathy with subcortical cysts (9 papers, 2016 to 2025). "In the mouse nervous system, HEPACAM (Hepatic And Glial Cell Adhesion Molecule, also known as GlialCAM) and MLC1 (Megalencephalic Leukoencephalopathy With Subcortical Cysts 1) stabilize CLCN2 in the plasma membrane by reducing its turnover rate and improving CLCN2 gating." (PMID 40140900, 2025).
hepatocellular carcinoma (5 papers, 2010 to 2022). A malignant tumor that arises from hepatocytes. "The HEPACAM gene, which encodes a cell adhesion molecule of the immunoglobulin family, was upregulated (14.9-fold, p=6.58e-4), in contrast to malignant tumors such as hepatocellular carcinoma, in which it is usually downregulated." (PMID 23354516, 2013). "The hepaCAM gene was first described in hepatocellular carcinoma and was also discovered in the central nervous system (CNS); it is named GlialCAM, based on the site of its identification." (PMID 35911693, 2022). "GlialCAM (also called HepaCAM) was identified as a putative tumour suppressor gene that is silenced in hepatocellular carcinoma." (PMID 31071485, 2019). "Studies have shown that the expression of hepaCAM is frequently lost in human hepatocellular carcinoma and processed a tumor suppressor gene." (PMID 20205955, 2010). "Previous studies have shown that the expression of hepaCAM is frequently completely suppressed in human hepatocellular carcinoma and significantly suppressed in a variety of other tumor types including malignancies of the lung, brain, colon, and blood." (PMID 20205955, 2010). "HepaCAM was recently demonstrated to be differentially expressed in human hepatocellular carcinoma." (PMID 20205955, 2010).
bladder cancer (3 papers, 2010 to 2021). "The overexpression of hepaCAM prevented the translocation of p-SMAD2/3 from the cytoplasm to the nucleus in bladder cancer cells." (PMID 35174173, 2021). "A gene expression analysis of hepaCAM-expressing and control bladder cancer cells identified a large number of differentially regulated genes, indicating that hepaCAM may mediate its growth-inhibitory effect via multiple pathways." (PMID 27819278, 2016). "However, the expression and biological function of hepaCAM has not been investigated in bladder cancer." (PMID 20205955, 2010).
Macrocephaly (2 papers, 2014 to 2019). Occipitofrontal (head) circumference greater than 97th centile compared to appropriate, age matched, sex-matched normal standards. "Mutations in the GLIALCAM gene (HEPACAM) have been recently identified in a spectrum of neurological conditions associated with macrocephaly." (PMID 24580998, 2014).
prostate carcinoma (2 papers, 2021 to 2024). A carcinoma that arises from epithelial cells of the prostate gland. "Expression of hepaCAM was inversely related to the HOTAIR in prostate cancer due to repression of hepaCAM promotor by HOTAIR-mediated recruitment of PRC2 and downregulation of hepaCAM promoted metastasis by the abnormal activation of MAPK signalling pathway." (PMID 40176927, 2024). "HOTAIR depletion regenerated hepaCAM levels in the cells and restricted cancer growth and metastasis, indicating HOTAIR/hepaCAM/MAPK axis to be a potential therapeutic roadway for prostate cancer." (PMID 40176927, 2024). "Therefore, we concluded that hepaCAM acts as a key bridge molecule in the process of distant metastasis that is altered by HOTAIR in prostate cancer." (PMID 33024272, 2021). "Therefore, the HOTAIR/hepaCAM/MAPK axis may provide a new avenue towards therapeutic strategies and prognostic indicators for advanced prostate cancer." (PMID 33024272, 2021).
autoimmune hepatitis (1 paper, 2025). Hepatitis caused by autoantibodies. "If glialCAM/HepaCAM were driving MS as an inflammatory autoantigen, one would expect comorbid autoimmune hepatitis and astrocytic pathology analogous to anti-aquaporin-4 associated neuromyelitis optica." (PMID 40327539, 2025).
benign prostatic hyperplasia (1 paper, 2021). A non-cancerous nodular enlargement of the prostate gland. "The expression of hepaCAM and H3K27me3 in 70 PCa specimens and 25 benign prostatic hyperplasia (BPH) samples was examined by immunohistochemistry (IHC)." (PMID 33024272, 2021).
bladder (1 paper, 2010). "In conclusion, we found that hepaCAM is frequently suppressed in TCCB, the most common bladder malignancy in humans." (PMID 20205955, 2010).
colorectal cancer (1 paper, 2020). A primary or metastatic malignant neoplasm that affects the colon or rectum. "A recent study has shown that HEPACAM was expressed at low level, and HEPACAM overexpression inhibited cell proliferation, migration, and invasion in colorectal cancer." (PMID 32522293, 2020).
schwannoma (1 paper, 2013). A benign, usually encapsulated slow growing tumor composed of Schwann cells. "Therefore, HEPACAM gene overexpression concomitant with CAV1 downregulation may participate in schwannoma development and/or maintenance and some members of the immunoglobulin superfamily appear deregulated in schwannomas." (PMID 23354516, 2013).
transitional cell carcinoma of bladder (1 paper, 2010). "Therefore we sought to examine hepaCAM expression and the relationship between its structure and function in human transitional cell carcinoma of bladder (TCCB)." (PMID 20205955, 2010).
cancer (12 papers, 2010 to 2026). A tumor composed of atypical neoplastic, often pleomorphic cells that invade other tissues. "The hepaCAM gene encodes a new immunoglobulin-like cell adhesion molecule, and its expression is suppressed in a variety of human cancers." (PMID 20205955, 2010). "In RCC, Cancer-derived sEVs have been demonstrated to downregulate hepatocyte cell adhesion molecule (hepaCAM) expression in RCC in a p-AKT-dependent way." (PMID 37469514, 2023). "Their findings revealed the important role of the p-SMAD2/3 pathway in hepaCAM-induced apoptosis of cancer cells, and provided valuable insights for current and future clinical trials of Ad-hepaCAM and p-SMAD2/3." (PMID 35174173, 2021). "The IHC staining intensity detected by ImageJ revealed that H3K27me3 in the tumour tissues was significantly higher than that in the BPH tissues, and the intensity was increased with carcinoma progression, while hepaCAM showed the opposite pattern." (PMID 33024272, 2021). "HepaCAM (GlialCAM) is frequently deleted in carcinomas, and reintroduction of hepaCAM into transformed cell lines reduces cellular growth and induces senescence." (PMID 27819278, 2016). "We further explored the relationship between MAPK signalling and hepaCAM in cancer migration." (PMID 33024272, 2021). "Since hepaCAM increases connexin 43 levels, and promotes its trafficking from the cytoplasm to cellular junctions, the deletion of either gene may have similar growth-promoting effects for cancer cells." (PMID 27819278, 2016). "Moreover, contactin-5 (CNTN5), 26S proteasome non-ATPase regulatory subunit 14 (PSMD14), hepatic and glial cell adhesion molecule (HEPACAM) and hepatocellular Carcinoma, Down-Regulated 1 (HEPN1) are four genes associated with suicidality." (PMID 36979315, 2023).
tumor (9 papers, 2010 to 2023). "HEPACAM family member 2 (HEPACAM2) is a paralog of Hepatocyte Cell Adhesion Molecule (HEPACAM), which is known to act as a tumor suppressor by promoting differentiation." (PMID 31337362, 2019). "Perhaps the most interesting of these targets is HepaCAM (11q24.2), a gene already known to play a tumour suppressor role in different cancers and already found hyper-methylated in these neoplasias." (PMID 28662712, 2017). "Among the 56 hypomethylated-repressed genes, two candidate tumor-suppressor genes were identified, the hepatic and glial cell adhesion molecule (HEPACAM) and the ABI family, member 3 (NESH) binding protein (ABI3BP)." (PMID 25945129, 2015). "In five fresh PCa surgical specimens and the corresponding adjacent normal tissues, the HOTAIR mRNA and H3K27me3 protein levels were significantly higher in the tumour tissues (T) than in the adjacent normal tissues (N), while the mRNA and protein levels of hepaCAM showed the opposite pattern." (PMID 33024272, 2021). "By discovering the requirement of hepaCAM for localizing connexin 43, a well-established tumor suppressor, to cellular junctions and stabilizing it there, this study suggests a mechanism by which deletion of hepaCAM may support tumor progression." (PMID 27819278, 2016). "Since connexin 43 has anti-tumor activity, its regulation by hepaCAM may explain the anti-tumor activity of hepaCAM." (PMID 27819278, 2016). "By discovering the requirement of hepaCAM for localizing connexin 43, a well-established tumor suppressor, to cellular junctions and stabilizing it there, this study identifies a mechanism by which deletion of hepaCAM may support tumor progression." (PMID 27819278, 2016). "Additionally, hepaCAM possesses properties often observed in tumor suppressor genes." (PMID 20205955, 2010).
HEPACAM also shares sentences with these, for which no sentence is quoted: leukodystrophy (8 papers); Leukoencephalopathy (4); astrocytoma (2); Autoimmunity (2); melanoma (2); neurodegenerative disease (2); Ataxia (1); autism (1); autism spectrum disorder (1); autoimmune disease (1); brain ischemia (1); channelopathy (1); epilepsy (1); experimental autoimmune encephalomyelitis (1); glioblastoma (1); glioma (1); infection (1); inflammation (1); Intellectual disability (1); latent infection (1); leiomyoma (1); leiomyosarcoma (1); liver cancer (1); liver neoplasm (1); megalencephaly (1); neuroblastoma (1); neuromyelitis optica (1).